AHR (aryl hydrocarbon receptor)
Diseases named in the same sentence as AHR in open-access papers (continued):
Sharing a sentence is not in itself a finding about the gene and the disease.
prostate carcinoma (continued). "AHR suppresses the viability and migration of human prostate cancer LNCaP cells, and plays pivotal role in cancer by modulating the downstream expression of Mitogen-Activated Protein Kinase Kinase Kinase 12 (MAP3K12)." (PMID 30972102, 2019). "Extensive in vitro and in vivo studies have established a role for AhR in prostate and prostate cancer development." (PMID 31328183, 2018). "Compared with AhR+/+ transgenic adenocarcinoma of the mouse prostate (TRAMP) mice, AhR−/− TRAMP mice showed a higher incidence of prostate cancer accompanied by an increase in VEGF." (PMID 29984241, 2018). "Evidence has shown that AhR is constitutively active in advanced prostate cancer cell lines which model castration resistant prostate cancer (CRPC)." (PMID 31328183, 2018). "Here we investigate the effect of simultaneous inhibition of the aryl hydrocarbon receptor (AhR) and Src on androgen receptor (AR) signaling in prostate cancer cells." (PMID 28671964, 2017). "AhR is constitutively active in advanced prostate cancer cell lines that model CRPC and where Src activity is also elevated." (PMID 28671964, 2017). "AhR has also been shown to regulate AR signaling which remains functionally important in the development and progression of prostate cancer." (PMID 28671964, 2017). "In the development of prostate cancer in transgenic adenocarcinoma of the mouse prostate (TRAMP) mice, AHR loss enhanced prostate carcinogenesis." (PMID 28878246, 2017). "The data presented here compares the effect of TCDD exposure on AhR and AR activity in androgen sensitive LNCaP cells versus castration resistant C4-2 prostate cancer cells." (PMID 26154658, 2015). "Androgen sensitive prostate cancer cells have significantly more cytoplasmic AhR complex than the castration-resistant C4-2 prostate cancer cells." (PMID 26154658, 2015). "Western blot analysis was used to evaluate AhR and AR protein expression in androgen-sensitive LNCaP and castration-resistant C4-2 prostate cancer cells in the presence of TCDD and R1881." (PMID 26154658, 2015). "Exposing a human prostate cancer cell line to the AHR agonists TCDD and/or benzo[a]pyrene (BaP) rapidly induced WNT5A expression and increased mRNA levels of FZD1, FZD3, and LEF1." (PMID 25286307, 2014). "The presence of nuclear AhR in grade 2 and grade 3 tissues along with the in vitro data from the prostate cancer cell lines suggest a transcriptionally active AhR in these higher grade tumors." (PMID 24755659, 2014). "AhR reactivity by Gleason score: Prostate cancer tissues were catorized based upon Gleason score 2–6 (well differentiated), 7 (moderately differentiated) or 8–10 (poorly differentiated)." (PMID 24755659, 2014). "Advance prostate cancer cell lines have an increase in the expression of AhR mRNA and protein compared to the androgen sensitive, LNCaP, cell line." (PMID 24755659, 2014). "Further studies are needed to determine the effect of increased AhR expression on CDK4 activity in advanced prostate cancer cells." (PMID 24755659, 2014). "Immunoblot analysis showed that AhR expression is increased in androgen independent (C4-2) prostate cancer cells when compared to androgen sensitive (LNCaP) cells." (PMID 24755659, 2014). "The Cignal XRE reporter was used to measure the basal activity of the AhR signaling pathway in advanced prostate cancer cell lines." (PMID 24755659, 2014). "Immunohistochemical staining of prostate cancer tissues revealed increased nuclear localization of AhR in grade 2 and grade 3 cancers compared to the well differentiated grade 1 cancers." (PMID 24755659, 2014). "We have previously reported that AhR is required to maintain hormone independent signaling and growth by the androgen receptor in C4-2 prostate cancer cells." (PMID 24755659, 2014). "This evidence shows a direct role for AhR in androgen receptor dependent growth of prostate cancer cells." (PMID 24755659, 2014).
prostate carcinoma (continued). "Western blot analysis of cellular fractions revealed that the increase AhR expression in the advanced prostate cancer cell lines is accompanied by nuclear accumulation of AhR without stimulation by an exogenous ligand." (PMID 24755659, 2014). "The ability of constitutive AhR signaling to regulate cell cycle progression in advanced prostate cancer cells makes AhR a possible target for treatment of HRPC." (PMID 24755659, 2014). "In this present study we show that AhR is constitutively active in advanced prostate cancer cells and that ablation of constitutive AhR signaling to inhibit androgen independent growth is not dependent on androgen receptor status." (PMID 24755659, 2014). "The expression and localization of AhR was assessed in prostate cancer tissue by immunohistochemical staining." (PMID 24755659, 2014). "In contrast, the advanced prostate cancer cells lines showed high expression of the AhR protein in the nuclear fractions." (PMID 24755659, 2014). "The assay used to test AhR promoter activity revealed that the advance prostate cancer cells DU145, PC3 and PC3M, all possess a high level of AhR binding to XRE in the absence of an exogenous ligand." (PMID 24755659, 2014). "Together, these results show that AhR is constitutively active in advanced prostate cancer cell lines that model hormone refractory prostate cancer." (PMID 24755659, 2014). "LNCaP, DU145, PC3 and PC3M prostate cancer cells were grown in the presence of AhR inhibitor CH223191191 in concentrations ranging from 1 μM to 50 μM." (PMID 24755659, 2014). "This notion was supported by previous reports demonstrating an inhibitory role for the AhR pathway in prostate cancer." (PMID 20140206, 2010). "Our studies indicate a novel ligand independent strategy of boosting AhR expression as means of suppressing prostate cancer growth." (PMID 20140206, 2010). "Recent studies revealed a connection between the AhR pathway and prostate cancer both in vitro and in vivo, showing that the AhR interacts and inhibits the AR." (PMID 20140206, 2010). "Observing AhR upregulation upon β-TrCP inhibition in prostate cancer cells prompted us to inspect AhR status in various stages of prostate cancer." (PMID 20140206, 2010). "Overexpression of the AhR has been detected in a number of cancerous and pre-cancerous lesions including breast and prostate cancer." (PMID 20565777, 2010). "These genes were enriched primarily in 43 pathways, including apoptosis and prostate cancer pathways, suggesting that AhR might specifically activate the apoptosis pathway to respond to ADT." (PMID 40759641, 2025). "After normalization, we found that 135 genes enriched primarily in spliceosome, ribosome biogenesis in eukaryotes, and ribosome biogenesis processes were regulated by AhR in all three cell conditions, indicating the essential role of AhR signalling in prostate cancer." (PMID 40759641, 2025). "Recent studies suggest that AA men may exhibit higher levels of AHR expression in prostate cancer tissues, potentially contributing to more aggressive tumor behavior." (PMID 39600743, 2024). "Moreover, the agonist of AhR reduced to some extent urolithin A-mediated increase in PBMCs NK activity in patients with prostate cancer (p = 0.3)." (PMID 39850551, 2024). "Importantly, AHR signaling has been shown to influence several aspects of prostate cancer progression, including AR signaling, cell proliferation, and invasiveness." (PMID 39600743, 2024). "AA men show higher levels of AHR expression in prostate cancer tissues compared to Caucasian men, which may drive more aggressive tumor behavior and poorer clinical outcomes." (PMID 39600743, 2024). "Carbidopa, an AhR antagonist, has been shown to promote the ubiquitination and proteasomal degradation of AR, leading to a significant reduction in AR protein levels and decreased prostate cancer cell viability." (PMID 39184676, 2024).
prostate carcinoma (continued). "Notably, the AHR expression was significantly higher in CRPC tissues than in hormone-naive prostate cancer tissues, or in cell lines (available online)." (PMID 38410974, 2024). "However, recent research has expanded the significance of AHR beyond its role in xenobiotic metabolism, suggesting its involvement in tumorigenesis in various cancers, including prostate cancer." (PMID 39600743, 2024). "Other AhR antagonists have similarly demonstrated their ability to block AR activity and reduce tumor growth, providing a robust strategy for targeting hormone-refractory prostate cancer." (PMID 39184676, 2024). "Recent studies have highlighted the inhibitory crosstalk between AhR and AR in prostate cancer." (PMID 39184676, 2024). "Drugs capable of simultaneously modulating both AHR and AR signaling pathways could offer a more effective treatment strategy for prostate cancer patients, particularly those with castration-resistant prostate cancer (CRPC), who have limited treatment options." (PMID 39600743, 2024). "Higher AhR activity has been observed in more advanced and aggressive forms of prostate cancer, indicating that AhR could be used to stratify patients based on the likely progression of their disease." (PMID 39184676, 2024). "There is growing interest in targeting AHR as a therapeutic strategy in prostate cancer." (PMID 39600743, 2024). "Urolithin A increases the NK activity of PBMCs from patients with prostate cancer and healthy subjects, and the AhR may be involved in this capability of urolithin A." (PMID 39850551, 2024). "Thus, the interaction of AhR with various components of the immune system can either promote or inhibit prostate cancer progression, depending on the specific cellular and molecular context." (PMID 39184676, 2024). "Inhibit pro-tumorigenic effects of AHR, potentially reducing aggressiveness of prostate cancer." (PMID 39600743, 2024). "Given the elevated AHR activity observed in AA men, targeting AHR could be a promising approach to mitigating the aggressive nature of prostate cancer in this population." (PMID 39600743, 2024). "Differences in AHR signaling pathways may contribute to the observed ethnic disparities in prostate cancer outcomes." (PMID 39600743, 2024). "AhR represents a multifaceted and promising target in prostate cancer therapy." (PMID 39184676, 2024). "The use of AhR as a biomarker for prostate cancer aggressiveness could provide valuable prognostic information, helping to stratify patients and tailor treatment approaches based on individual tumor characteristics." (PMID 39184676, 2024). "Investigating AHR signaling in the context of ethnic disparities is crucial, as the interaction between AHR and these pathways may contribute to the variability in prostate cancer development among different ethnic groups." (PMID 39600743, 2024). "Moreover, BaP affects the FAM227A expression by activating AhR and promoting enhancer activity, thereby inducing malignant behaviors of prostate cancer cells." (PMID 38410974, 2024). "The interaction between AHR and AR signaling pathways provides critical insight into how these molecular mechanisms may contribute to the aggressive nature of prostate cancer in AA men." (PMID 39600743, 2024). "AHR is expressed in prostate cancer cells and induces its known target genes CYP1A1 and CYP1B1." (PMID 37077937, 2023). "Additionally, it seems that different types of prostate cancer cells have shown different sensitivity to affecting the AR pathways through AhR activation." (PMID 36613955, 2022). "AhR was found to be constitutively active in advanced prostate cancer cell lines that mimic hormone-refractory prostate cancer, and increased nuclear AHR localization was positively associated with higher tumor grade, poor differentiation, and/or poor prognosis." (PMID 36324578, 2022).
prostate carcinoma (continued). "One such cross-talk can represent AhR-mediated AR degradation, since AhR has been demonstrated as a ligand-dependent E3 ubiquitin ligase that induces proteasomal degradation of AR in the androgen-sensitive prostate cancer cell line LNCaP." (PMID 36613955, 2022). "This may be due to the fact that different types of prostate cancer are diverse in AhR and AR receptor content, and subcellular localization, and that AhR presence may affect AR phosphorylation status." (PMID 36613955, 2022). "As a result of the emerging concept of bacterial mimicry, we tested whether compounds with indole scaffolds capable of AhR activation have the potential to restrict AR activity in prostate cancer cells." (PMID 36613955, 2022). "AhR-mediated antiandrogenic activity was proposed in prostate cancer cells." (PMID 36612408, 2022). "Interrupt of Trp/TDO2/Kyn/AhR/c-Myc loop with c-Myc inhibitor Mycro-3 efficiently suppressed the chemoresistance and improved the outcome of chemotherapy, which described a new strategy in clinical prostatic cancer treatment." (PMID 34657603, 2021). "Additionally, nimodipine (a calcium-channel blocker indicated for subarachnoid hemorrhage) and flutamide (an androgen receptor antagonist indicated for prostate cancer) for the first time were reported as compounds which competitively bind to the AhR in vitro." (PMID 32899152, 2020). "Moreover, the role of AHR linked with SP1 and IL warrants further investigation in context to prostate cancer." (PMID 30972102, 2019). "The molecular mechanism of AHR in prostate cancer needs further investigation." (PMID 30972102, 2019). "AhR helps to sustain androgen-independent growth of prostate cancer cells." (PMID 28671964, 2017). "Furthermore, co-inhibition of AhR and Src reduced the growth of prostate cancer cells compared to individual treatments." (PMID 28671964, 2017). "The ability of the AhR to function as a tumor suppressor in the absence of exogenous ligands has been demonstrated in a mouse model of prostate cancer, but this appears to be a context dependent effect, with some studies suggesting a pro-proliferative function of the AhR in cancer." (PMID 28424418, 2017). "However, this study is the first to suggest simultaneous inhibition of AhR and Src to inhibit AR signaling and prostate cancer cell growth." (PMID 28671964, 2017). "It was reported that Icaritin activated AHR in prostate cancer." (PMID 26376676, 2015). "Cytoplasmic and nuclear expression of AhR in prostate cancer tissues." (PMID 24755659, 2014). "Despite the overwhelming evidence of anti-proliferative activities of AhR ligands, accumulating evidence suggest that in advanced stages of prostate cancer AhR is constitutively active and may promote progression." (PMID 24755659, 2014). "Previous studies have determined an androgen dependent role for AhR in prostate cancer growth." (PMID 24755659, 2014). "Activation of AhR induces transcription of MMP-9 in advanced prostate cancer cells." (PMID 25068070, 2013). "In prostate cancer cells, AHR was identified as a target gene of the Wnt/β-catenin pathway." (PMID 23825972, 2013). "Taken together, these results indicate that salinomycin reduces the expression of key prostate cancer oncogenes and AR signalling as well as causes alterations in steroid biosynthesis, cell-cycle checkpoint regulation, AhR signalling and oxidative stress response in prostate cancer cells." (PMID 22215106, 2012). "However, many processes known to be modulated via AhR were altered in salinomycin-exposed prostate cancer cells." (PMID 22215106, 2012). "Moreover, AhR is overexpressed in prostate cancer and cancer stem cells and it can bind to NF-κB and promote activation of MYC." (PMID 22215106, 2012). "We therefore hypothesized that the upregulation of the AhR could be mediating the growth inhibitory effect of β-TrCP knockdown in prostate cancer cells." (PMID 20140206, 2010).
prostate carcinoma (continued). "Additionally, the switch in transcription factors from androgen receptor (AR) to glucocorticoid receptor (GR) modulated the persistent expression of TDO2, and the same TDO2-Kyn-AhR signalling pathway promoted the aggressive proliferation of prostate cancer cells in the ADT-resistant cell stage." (PMID 40759641, 2025). "Although TDO2 is highly expressed in the liver, which may hinder the development of TDO2 small molecule inhibitors, our study may advocate targeting TDO2-Kyn-AhR signalling as a new adjuvant therapy for androgen-sensitive prostate cancer patients treated with ADT." (PMID 40759641, 2025). "AHR is involved in various cellular processes relevant to cancer, including cell cycle regulation, modulation of the immune response, and interaction with hormone receptor signaling pathways, particularly the Androgen Receptor (AR) signaling pathway, which is central to prostate cancer progression." (PMID 39600743, 2024). "Nevertheless, the epigenetic mechanism of AhR and BaP in prostate cancer remains unclear." (PMID 38410974, 2024). "Taken together, these findings indicate that ADT-induced upregulation of TDO2 prevented ADT-induced death of dormant prostate cancer cells and preserved drug tolerance, whereas TDO2 or AhR inhibition promoted ADT-induced death of dormant cells." (PMID 40759641, 2025). "Studies in the transgenic, androgen-sensitive TRAMP model of prostate cancer show that AhR protects against prostate cancer development, as AHR+/+ TRAMP mice exhibit lower tumor formation than AHR-/- or AHR+/- TRAMP mice." (PMID 38807762, 2024). "Biologically, the rs6001092-G allele strengthened the transcription factor binding affinity to AhR, thereby upregulating FAM227A, especially upon exposure to BaP, which induced the malignant phenotypes of prostate cancer." (PMID 38410974, 2024). "The interaction between AhR and other signaling pathways, such as PI3K/AKT, adds another layer of complexity to prostate cancer progression." (PMID 39184676, 2024). "For the analysis of tumor suppressive functions of AhR in prostate carcinogenesis, AhR-null mice were genetically crossed with transgenic adenocarcinoma of the mouse prostate (TRAMP) model of prostate cancer." (PMID 37830596, 2023). "To this end, we employed specific inhibitors to TBK1 (GSK8612; GSK) and JAK1/2 (Ruxolitnib; Ruxo) in prostate cancer cell lines and induced PARP7 via AHR (PC3, DU145) and AR (PC3-AR)." (PMID 37077937, 2023). "We determined that RBN2397 inhibits the growth of prostate cancer cells dependent on transcriptional induction of PARP7, achievable by treating cells with androgen to activate AR, or with ligands that activate AHR." (PMID 37077937, 2023). "Studies on prostate cancer have confirmed that the interaction between TET3 and AHR can influence the expression of various factors." (PMID 37718440, 2023). "In multiple prostate cancer cell lines, PARP7 can be induced by treating cells with agonists for AR and AHR." (PMID 37077937, 2023). "More experiments are needed to define the relationship between AhR, AR and the differential effects of TCDD on prostate cancer at different stages." (PMID 26154658, 2015). "qRT-PCR and western blot analysis was used to determine AhR mRNA and protein expression in hormone sensitive LNCaP cells as well as hormone refractory DU145, PC3 and PC3M prostate cancer cell lines." (PMID 24755659, 2014). "Diesel exhaust particles, confirmed to be AhR agonist, inhibit DHT induced androgenic effects in PC3 prostate cancer cells." (PMID 24755659, 2014). "Inhibition of AhR signaling by direct inhibitor, CH223191, resulted in a substantial decrease in CYP1B1 levels in the advanced prostate cancer cell lines." (PMID 24755659, 2014). "Furthermore, AhR has been shown to interact with other signaling pathways such as PI3K/AKT, which further influences prostate cancer progression." (PMID 39184676, 2024).